SFRP2 (secreted frizzled related protein 2)
Diseases named in the same sentence as SFRP2 in open-access papers (continued):
Sharing a sentence is not in itself a finding about the gene and the disease.
cancer (continued). "We found that SFRP2 promoter methylation in whole blood is a promising prognostic factor for several cancer outcomes, such as stages, lymph node invasion and CRC recurrence, while SFRP2 promoter methylation in tumors is a potential predictor of treatment response." (PMID 38802858, 2024). "Interestingly, we also found strong upregulation of Cxcl15, Sfrp2, Dcn, and Ccdc80 genes when we compared TPC with KPC cancer cells." (PMID 37607005, 2023). "However, a recent study showed that some subtypes of SFRPs, such as SFRP2 and SFRP4, tended to be overexpressed in cancer." (PMID 35683460, 2022). "Five of these genes (ARID5B, BAZ2B, RABGAP1, SFRP2, WBP1L) are associated with cancer risk and cellular differentiation and have not been previously identified in MS studies." (PMID 36685876, 2022). "In addition, the expression of cancer stemness markers (Oct4, Lin28, Nanog, and Sox2) was obviously increased in SW1783 and SW1088 cells after SFRP2 knockdown." (PMID 34852024, 2021). "PIK3CA-mutant cancers displayed higher expression of 12 of the 17 Wnt genes compared to PIK3CA wild-type tumors, including five Wnt target genes (LEF1, MYCN, FZD7, SFRP2, and TNFRSF11B) and seven Wnt signaling components (TCF7L1, TCF7L2, CTNNB1, FZD4, SFRP1, WNT5A, and MSX2)." (PMID 34035258, 2021). "We examined the DNA methylation levels of SFRP1, SFRP2, SFRP5, DKK2, DKK3, mir34b/c, RASSF1A, IGFBP7, CDKN2A, and MLH1 in normal colonic crypts isolated from regions that were adjacent to the cancer, as well as distal and proximal regions (left and right sides)." (PMID 28533824, 2017). "We found that SFRP2 and 4 expression is tightly correlated to stromal content, and forms part of a common epithelial-to-mesenchymal transition (EMT) gene program that is expressed in a multitude of different cancers." (PMID 28218291, 2017). "This study was an attempt to compare CPUK02 with 5-AZA as DNMT inhibitor agent and evaluate whether it can induce its anti-cancer effects via altering the level of DNMT3b mRNA, MGMT and SFRP2 methylation pattern in HCT 116 cell line." (PMID 28090275, 2017). "Previous studies have shown that promoters of most WNT antagonistic genes (sFRP1, sFRP2, sFRP3, sFRP5, DKKs, and WIF1) are methylated or epigenetically silenced in RCC, which results in uninhibited WNT signaling during cancer initiation or progression." (PMID 23094073, 2012). "Consistent with the semi-quantitative MSP results, the mean methylation level of SFRP2 was significantly higher in cancer than in adjacent non-cancer specimen (P<0.001)." (PMID 17848950, 2007). "Consequently, SFRP2 is a potential tumor suppressor gene in CRC, which could be recommended as a therapeutic target for cancer clinical practice." (PMID 38802858, 2024). "Conversely, the SFRP family of proteins, notably SFRP4, SFRP2, and SFRP1, serve as antagonists to Wnt signalling and have demonstrated efficacy in diminishing CSC traits such as drug resistance, stemness, metastasis, and proliferation across various cancer types." (PMID 38136392, 2023). "Yet, the downregulation of the type II collagen gene (COL2A1) in PC3SFRP2, which is involved in cancer stemness in various cancer types, and the upregulation of CDH15 (Cadherin 15) in PC3SFRP2, which mediates intracellular adhesion, are promising predictors of the role of SFRP2 in cancer metastasis." (PMID 36552843, 2022). "Doing a differential expression between the two clusters of cancer fibroblasts, we found metastatic fibroblasts were found to express higher levels of soluble factors compared to primary fibroblasts including, CXCL12, S100A6, S100A10, SFRP2,SFRP4,IGF1, CXCL14, ANGPTL4 and IL6." (PMID 30383866, 2018). "Based on analysis of the SFRP2 promoter methylation status and the expression levels of SFRP2 in cancer tissues and adjacent non-cancer tissues from OSCC patients, the present study investigated the effects of SFRP2 on the Wnt signaling pathway in the development of OSCC in vivo and in vitro." (PMID 25189527, 2014).
cancer (continued). "Moreover, methylated SFRP2 was detected in 66.7% of serum samples from cancer patients but not in normal controls." (PMID 17848950, 2007). "Secreted frizzled-related protein 2, a secreted protein involved in the non-canonical WNT calcineurin/ NFAT pathway in endothelial cells, is a validated therapeutic target for cancer." (PMID 34070758, 2021). "By comparing OVCAR3 control to OVCAR3 with WNT + RSPO + SFRP2, we observed pronounced global protein level changes with indications of WNT signalling activation, with significant overexpression of WNT11, a non-canonical WNT signalling molecule with a role in cancer." (PMID 38361045, 2024).
cardiovascular diseases (6 papers, 2020 to 2024). "Here, we review the role of sFRP2 and Wnt signaling in cardiac development and cardiovascular disease." (PMID 32071544, 2020). "This review will focus on the importance of sFRP2 in cardiac development and cardiovascular disease." (PMID 32071544, 2020). "Secreted frizzled-related protein 2 (sFRP2), a vital molecule of Wnt signaling, can regulate cardiac development and cardiovascular disease." (PMID 32071544, 2020). "Secreted frizzled-related protein 2 (sFRP2) is involved invarious cardiovascular diseases." (PMID 39076470, 2024). "This proposal takes into consideration the ex vivo studies showing that SFRP2 may exert multiple other protective roles in different pathophysiological processes of cardiovascular disease, including inducing angiogenesis and inhibiting cardiomyocyte apoptosis." (PMID 32454934, 2020).
infection (4 papers, 2014 to 2023). The state of being infected such as from the introduction of a foreign agent such as serum, vaccine, antigenic substance or organism. "Conversely, control mice exhibit greater expression of Ccl5, Mmp8, Sfrp2, Tmem119, and Tnn after 14 days of infection." (PMID 37845223, 2023). "Next, we ectopically over‐expressed SFRP2 in SCAPs by infection with a retroviral construct expressing SFRP2." (PMID 31568642, 2020). "Then, we designed a short hairpin RNA (shRNA) to target SFRP2 and introduced it into SCAPs via lentiviral infection (SCAP-SFRP2sh cells)." (PMID 28794794, 2017).
adenocarcinoma (3 papers, 2015 to 2024). A common cancer characterized by the presence of malignant glandular cells. "In summary, our study revealed high expression of the SFRP2 gene in pericyte cells during the liver metastasis of adenocarcinoma of the esophagogastric junction (AEGJ) using 10X single-cell sequencing." (PMID 39850884, 2024).
cardiac diseases (2 papers, 2014 to 2025). "Thus, sFRP2 is an important molecule for the biogenesis of a new regenerative phenotype character in MSCs, and Wnt signaling is a therapeutic target for heart diseases." (PMID 25101130, 2014).
digestive system cancer (1 paper, 2026). A primary or metastatic malignant neoplasm involving any part of the digestive system. "Notably, the SDC2 marker displayed zero false positives among 98 digestive system cancer cases within the control groups, while SFRP2 and TFPI2 showed 8.16% and 10.2% false-positive rates, respectively." (PMID 41695361, 2026).
inflammation (1 paper, 2021). Aberrant reaction of the microcirculation characterized by movement of fluid and leukocytes from the blood into extravascular tissues. "Thus, further studies are mandated to explore the detailed roles of sFRP2 in cardiovascular inflammation." (PMID 34722660, 2021).
SFRP2 also shares sentences with these, for which no sentence is quoted: keloid (3 papers); basal cell carcinoma (2); colon adenocarcinoma (2); craniorachischisis (2); hyperplastic polyp (2); idiopathic pulmonary fibrosis (2); ischemic heart disease (2); leukemia (2); liver cancer (2); metastasis (2); systemic sclerosis (2); triple-negative breast carcinoma (2); type 2 diabetes mellitus (2); acute myeloblastic leukemia (1); acute myocardial infarction (1); alveolar soft part sarcoma (1); Amoebiasis (1); atherosclerosis (1); atopic dermatitis (1); autism (1); benign tumours (1); bone sarcoma (1); bone tumor (1); brain glioma (1); carcinoma in situ (1); cervical adenocarcinoma (1); cholesteatoma (1); colorectal polyps (1); diabetic kidney disease (1); discoid lupus erythematosus (1).
A further 26 diseases each share a sentence with SFRP2 in 1 paper.